RNU2-44P (RNA, U2 small nuclear 44, pseudogene)
Gene: Small nuclear RNA gene on chromosome 4 (154,790,291 to 154,790,484, forward strand). Ensembl gene ENSG00000252604.
Homologues: Orthologues: tropical clawed frog U2 (61% identical), tropical clawed frog U2 (60% identical), tropical clawed frog U2 (59% identical), tropical clawed frog U2 (58% identical), tropical clawed frog U2 (57% identical), zebrafish U2 (57% identical), tropical clawed frog U2 (56% identical), tropical clawed frog U2 (55% identical), zebrafish U2 (55% identical), tropical clawed frog U2 (38% identical). Paralogues in human: RNU2-14P (46% identical), RNU2-48P (46% identical), U2 (46% identical), RNU2-59P (45% identical), U2 (45% identical), RNU2-2 (45% identical), RNU2-40P (45% identical), RNU2-61P (45% identical), RNU2-64P (45% identical), RNU2-62P (44% identical), RNU2-26P (44% identical), RNU2-36P (44% identical), and 66 more.